INS (insulin)
Diseases named in the same sentence as INS in open-access papers (continued):
Sharing a sentence is not in itself a finding about the gene and the disease.
Hyperglycemia (continued). "Consistently, managing acute hyperglycemia through insulin infusion has been suggested to improve clinical outcomes, while implementing chronic glycemic control positively affects immune response following vaccination." (PMID 35329890, 2022). "As a result of the strong impact of inflammatory and autoimmune reactions, β-cells undergo apoptosis, and impaired insulin secretion in β-cells affects the development of hyperglycemia." (PMID 36248900, 2022). "Our findings support the fact that increased weight by itself cannot promote intermediate hyperglycemia and that it needs to be stimulated by insulin." (PMID 35757631, 2022). "It is a multifactorial chronic disease characterized by hyperglycemia, altered insulin secretion, and/or impairment in insulin action." (PMID 35370943, 2022). "Next stages of the disease eventually lead to hyperglycemia and hyperinsulinemia as the circulating blood glucose increases which pressures the beta-cells of the pancreas to secrete extraordinary amounts of insulin." (PMID 35356248, 2022). "HIF1α stability and function are dysregulated by hyperglycemia, and disruption of this aberrant signaling can improve insulin sensitivity." (PMID 36531496, 2022). "The goal of insulin treatment is to reduce hyperglycemia to normal ranges, which will improve quality of life by relieving symptoms and preventing the complications of DM." (PMID 35203115, 2022). "Mice lacking functional VDR are unable to synthesize adequate insulin in response to hyperglycemia, and their pancreatic β-cells showed a lower amount of stored insulin, suggesting vitamin D-dependent insulin synthesis and secretion." (PMID 35859985, 2022). "Their beta cells show abnormal cycle progression and as a result these mice exhibit hyperglycemia and reduced insulin levels." (PMID 35805898, 2022). "Both strategies resulted in benefits from a metabolic perspective including improved hyperglycaemia and insulin sensitivity." (PMID 36101976, 2022). "In contrast, an elevated Se concentration upregulates PTP1B and induces suppressed insulin signaling and hyperglycemia." (PMID 35883754, 2022). "The protective effect of genistein against high-fat-diet-induced hyperglycemia and fatty liver attributes to activate hepatic insulin signaling pathway." (PMID 36570152, 2022). "Unfortunately, in that study, male PK-Ins1+/-;Ins2-/- mice developed hyperglycemia at a very young age because of insufficient endogenous insulin production, which limited our conclusions to female mice." (PMID 35189981, 2022). "They found that the massive expression of PDX-1 promoted the expression of the insulin gene, which resulted in the amelioration of hyperglycemia symptoms in diabetic model mice." (PMID 36551213, 2022). "Myristic acid was announced to improve hyperglycemia by decreasing insulin-responsive glucose levels in Nagoya-Shibata-Yasuda (NSY) mice." (PMID 35408706, 2022). "Even in the presence of identical insulin concentrations hyperglycemia is shown to increase intramuscular glycogen usage." (PMID 36083870, 2022). "Broiler chickens contain almost double the level of blood glucose compared with mammals and the impairment of insulin sensitivity prior to observations of hyperglycaemia are related to altered BCAA and AAA metabolism." (PMID 35353869, 2022). "Many antidiabetic medicines are now commercially available to treat hyperglycemia, most of which function through improving insulin sensitivity, supplementing insulin, increasing insulin secretion, and stimulating glucose absorption." (PMID 36557843, 2022). "In response to this, and to avoid excessive hyperglycemia and glucose intolerance, important adaptations occur in β-cell function, such as increased proliferation and glucose-stimulated insulin secretion." (PMID 36421415, 2022).
Hyperglycemia (continued). "Myo-inositol in the form of phosphate derivatives (inositol phosphoglycans) exerts an insulin-mimetic activity, acting downstream of insulin receptors to reduce hyperglycemia and promote muscular gluconeogenesis." (PMID 36239863, 2022). "Very recently, there have been reports in the literature of an effect of dual agonists (GIP/GLP-1) having a positive impact on glycemic control and improving insulin sensitivity, thus reducing complications related to hyperglycemia." (PMID 35205155, 2022). "For example, high glucose concentrations (hyperglycemia) necessitate quick insulin delivery, and these hydrogels can release insulin when needed without requiring any patient input." (PMID 36072265, 2022). "Hyperglycemia is a common metabolic dysfunction of Pheochromocytoma patients, mostly because of impaired insulin secretion and insulin sensitivity." (PMID 35669692, 2022). "We posit that a moderate and transient post-prandial hyperglycemia in the presence of insulin sensitivity, facilitates entry and use of glucose by monocytes and other immune cells, for more effective immune control of M.tb." (PMID 36558885, 2022). "This combination synergistically reduces fasting hyperglycemia, hyperlipidemia, and hypertension; improves peripheral and hepatic insulin sensitivity; alleviates hepatic oxidative stress and inflammation; and prevents lipid accumulation in the WAT and liver." (PMID 36615764, 2022). "In adult zebrafish, knocking out the pdx1 gene (a gene implicated in the development of type 2 diabetes) results in a reduced number of pancreatic β-cells, in decreased insulin levels and, consequently, hyperglycemia." (PMID 35628176, 2022). "Hyperglycaemia is due to impaired insulin secretion or impaired insulin because of pancreatic beta-cell dysfunction or insulin resistance." (PMID 35918636, 2022). "STZ damages pancreatic β-cells, which secrete insulin, thus inhibiting glucagon secretion and inducing hyperglycemia." (PMID 36104518, 2022). "Fourteen patients (8.1%) developed hyperglycemia during the course of their illness; 11 patients required inpatient insulin therapy with a median duration of 3 days (IQR, 3-20 days; range, 1-325 days)." (PMID 36367723, 2022). "Insulin, it was reported, prevents bothersome hyperglycemia symptoms such as increased thirst, frequent urination, and body discomforts (pains or aches), which improves sleep quality, which in turn improves happiness, health, and quality of life.I am fine." (PMID 35854336, 2022). "Insulin aids in preventing hyperglycemia partly by subduing glycogenolysis and gluconeogenesis while promoting glycogenesis." (PMID 36301972, 2022). "One of the most common features of T2D is impairments in insulin actions and signaling, which leads to hyperglycemia and hyperinsulinemia." (PMID 35458596, 2022). "Blockade of insulin signaling prevents glucose transport into cells and gradually leads to accumulation of glucose (hyperglycemia) when continuously supplied with food." (PMID 35563135, 2022). "To data, various studies have demonstrated the efficancy of ANT to ameliorate hyperglycemia and insulin sensitivity and to protect β cells, increase secretion of insulin in diabetic mice." (PMID 36335368, 2022). "The studies demonstrated improvements in healthcare outcomes such as glycaemic control, greater confidence with insulin administration and reduced occurrences of hypoglycaemia and hyperglycaemia and decreased length of hospital stay and healthcare costs." (PMID 36992734, 2022). "T2D is a metabolic condition defined by hyperglycemia in the presence of decreased insulin sensitivity and insulin level that affects millions of individuals worldwide." (PMID 36314741, 2022). "It has been well established that exercise reduces circulating insulin levels and improves the insulin response to hyperglycemia." (PMID 35264977, 2022).
Hyperglycemia (continued). "Concisely, SARS-CoV-2 binds to ACE2, which is expressed in a very high percentage in the pancreatic cells, thus API will occur with insulin secretion impairment and hyperglycemia development, worsening the condition if DM is preexistent." (PMID 36355535, 2022). "It is characterized by an autoimmune response against pancreatic islet antigens including insulin, which eventually leads to pancreatic β-cell depletion and, consequently, abolished insulin production resulting in hyperglycaemia." (PMID 35742925, 2022). "GDM is characterized by the inability of pancreatic beta cells to respond adequately to increased insulin requirements during pregnancy, resulting in varying degrees of hyperglycemia." (PMID 35207731, 2022). "DM is characterized by hyperglycemia, attributed to unbalanced glucose homeostasis by immune-mediated insulin deficiency (type 1 DM, T1DM), or by insulin resistance and disturbed insulin secretion (T2DM)." (PMID 36547931, 2022). "Along these lines, signal transduction in insulin flagging is weakened, bringing about hyperglycemia." (PMID 35268815, 2022). "Hyperglycemia and hyperlipidemia, characteristic of T2D, further fuel inflammation, adding to the impairment and damage to insulin-producing and insulin-sensitive tissues and organs through the mechanisms that underlie glucose toxicity and lipotoxicity." (PMID 35831885, 2022). "The need for insulin treatment in GDM is an important clinical indicator of the degree of hyperglycaemia." (PMID 36078508, 2022). "We can propose that flagellin induces insulin hypersecretion in early stages of the disease and longitudinal studies need to be done to show that this results in hypoinsulinemia and hyperglycemia over time." (PMID 35984746, 2022). "By the time hyperglycemia develops, reductions in both insulin sensitivity and in β-cell function have already occurred." (PMID 35453469, 2022). "C57 BLKS/JGPT db/db mice are characterized by IR and hyperglycemia due to their knocked-out leptin receptors, and their external insulin cannot control the levels of blood glucose and hepatic gluconeogenesis." (PMID 35267269, 2022). "In animal model of type 2 diabetes leptin-deficient (ob/ob) mice, mechanical and thermal hyperalgesia coincided with hyperglycemia observed early in life of these animals, and was reversible with insulin pretreatment." (PMID 35419564, 2022). "The aim of these treatments is to reduce hyperglycemia by activating the endogenous secretion of insulin with sulphonylureas and glitinides or by improving the sensitivity of target tissues to insulin with thiazolidinediones and biguanides." (PMID 36204130, 2022). "A more recent study that used flash-glucose monitoring on insulin-treated patients during Ramadan showed an increase in time in hyperglycemia and a reduced time in the target range." (PMID 35634376, 2022). "Initiate insulin therapy for persistent hyperglycemia (>180 mg/dl)Treatment goal: 140 - 180 mg/dl if achievable without significant risk for hypoglycemia." (PMID 35831938, 2022). "Treatment with NAC attenuated fasting hyperglycemia, IR, and hypertension and improved peripheral insulin sensitivity in HFD and IR animal models." (PMID 36615764, 2022). "This cohort study compares the use of a bayesian vs frequentist trial design in the Stroke Hyperglycemia Insulin Network Effort trial." (PMID 35544137, 2022). "Due to hyperglycemia and reduced insulin content in TgH mice, we examined α-cell distribution and glucagon contents in HFD-fed mice at 18-week-old." (PMID 35831364, 2022). "This is the therapy that most closely resembles physiological insulin secretion, releasing minimum doses of insulin continuously (basal infusion) and one-off doses at prandial times or to correct hyperglycemia (bolus infusion)." (PMID 35183150, 2022). "Insulin secreting beta cells (designed to compensate hyperglycemia) were incompetent in our study groups, resulting in low levels of C-peptide and hyperglycemia." (PMID 35204293, 2022).
Hyperglycemia (continued). "Insulin is a pancreatic hormone, and secreted in response to the increase of blood concentration of glucose (hyperglycemia), to promote circulating glucose to enter effector cells." (PMID 36465655, 2022). "A possible reason is that the insulin levels in IGT people are much higher than people with NGT at the presence of a mild hyperglycemia." (PMID 35090539, 2022). "A previous study from our laboratory had demonstrated that in-vivo administration of H19 siRNA induced hyperglycemia, hyperinsulinemia, hyperlipidemia and impaired oral glucose, insulin and pyruvate tolerance in mice." (PMID 35842608, 2022). "They potentially can reduce postprandial hyperglycemia by inhibiting glucose uptake and its release from the intestine to the liver, stimulating insulin secretion by the pancreas, and increasing glucose uptake by muscles and adipocytes." (PMID 35796695, 2022). "Sustained hyperglycemia in T2D impairs insulin-stimulated glucose uptake and utilization by peripheral tissues, including the liver, which gives rise to insulin resistance (IR)." (PMID 36466390, 2022). "Taken together, these data suggest that glucose-6-phosphate (G6P) or a downstream metabolite, rather than glucose itself, mediates most of the effects of chronic hyperglycaemia on insulin content, β-cell metabolism and insulin secretion." (PMID 36376280, 2022). "Bariatric and metabolic surgeries have been shown to improve hyperglycemia, insulin sensitivity, and hyperlipidemia." (PMID 36277729, 2022). "Insulin administration inhibits the glucose-sensing system in rainbow trout brains, and glucagon antagonizes insulin effects in fish, resulting in rapid and wide-ranging hyperglycemia." (PMID 36860440, 2022). "When hIAPP, which is co-secreted with insulin, misfolds and accumulates in the space between β cells and islet capillaries, it increases the likelihood of hyperglycaemia while also occurring alongside it." (PMID 36128718, 2022). "Most current therapies reduce hyperglycaemia by improving insulin sensitivity or insulin replacement." (PMID 35580081, 2022). "GLP-1 is a hormone with blood glucose-lowering action during hyperglycemia, and it induces insulin secretion and reduces glucagon secretion in a glucose-dependent manner." (PMID 35208221, 2022). "This hyperglycemia has a gluco-toxic effect on Langerhans beta cells, resulting in a reduction in insulin secretion." (PMID 35315990, 2022). "In diabetic PDA patients, hyperglycemia and high insulin level are both signals for poor prognosis, but insulin is an essential drug in regulating blood glucose levels." (PMID 35252207, 2022). "For patients with a blood glucose of over 300 mg/dL, insulin therapy can be initiated to quell the hyperglycemia, but it is preferable to use non-insulin therapies whenever possible." (PMID 36012526, 2022). "This metabolic disorder shows prominence of hyperglycemia and includes defects of insulin productions or insulin secretion or both." (PMID 35528161, 2022). "For instance, in mice fed for 3 months with ASA-supplemented diet (30 mg/kg), ASA reversed hyperinsulinemia and hyperglycemia bringing insulin and glucose to normal levels after 2 months of treatment." (PMID 35213966, 2022). "Significant problems of pediatric patients with T1D are maintaining glucose blood level stable via proper insulin dosage and managing with acute complications (hypo- and hyperglycemia)." (PMID 34999914, 2022). "Another ob/ob model, in which the leptin mutation is found in an insulin-resistant BTBR strain, is the BTBR ob/ob, leading to early T2DM development and maintenance of hyperglycemia, compared with other ob/ob models, as the animal become overweight/obese." (PMID 35409324, 2022). "This agreement coincides with ADA/EASD guidelines which recommend that patients on dual or triple therapy where HbA1c is above the individual target, or in those with extreme and symptomatic hyperglycemia or HbA1c > 10, insulin therapy should be initiated." (PMID 36554673, 2022).
Hyperglycemia (continued). "Hyperglycaemia and impaired insulin signaling promote systemic inflammation and activation of the sympathetic nervous system." (PMID 35529461, 2022). "As a metabolic disorder resulting from defective insulin secretion and insulin action, DM is characterized by a state of hyperglycemia." (PMID 36213282, 2022). "As well as delaying the onset of hyperglycaemia, desHis1Pro4Glu9-glucagon, and particularly desHis1Pro4Glu9-glucagon(Lys12PAL), improved glucose handling and insulin action in addition to augmenting pancreatic insulin stores." (PMID 36005280, 2022). "As a result, these studies showed that insulin reversed depressive behaviors and hyperglycemia-induced damage in the brain." (PMID 36552776, 2022). "The antihyperglycemic activity of sinapinic acid has been researched using a hyperglycemia model that was established by intraperitoneal injection of streptozotocin to destroy insulin-secreting pancreatic cells." (PMID 35465261, 2022). "In our analysis, 1-h PG was an independent predictor of hyperglycemia relapse even after adjusting for treatment with an oral antidiabetic agent after insulin discontinuation." (PMID 35721763, 2022). "They measured the levels of C-peptide, a direct indicator of endogenous insulin production, and postulated that hyperglycemia in patients with critical COVID-19 was due to the development of IR and not to a deficiency of pancreatic beta cells." (PMID 36312630, 2022). "It is characterized by elevated blood glucose (hyperglycemia) occurring due to malfunctions in insulin action, insulin production or both." (PMID 36297381, 2022). "Our results suggest that insulin secretory defects in CF affect growth prior to the development of fasting hyperglycemia." (PMID 35358060, 2022). "First, as improvement in hyperglycemia is seen in most patients, counseling and close monitoring of those treated with insulin or other medications is needed to modify therapy and avoid hypoglycemia." (PMID 34988348, 2022). "Decreased glucose absorption, increased serum insulin concentration, reduced postprandial hyperglycemia, and modulation of liver enzymes are the proposed mechanisms of action of these metabolites." (PMID 36678714, 2022). "Hyperglycemia can occur because of increasing levels of stress hormones e.g., catecholamines, steroids, glucagon and decreasing levels of insulin due to stress." (PMID 35586740, 2022). "The aim of this study is to explore the daily insulin dose and the percentage change in preprandial and basal insulin dosage of women with different types of hyperglycemia in pregnancy (HIP) during the whole gestation and postpartum period." (PMID 36339424, 2022). "The disease is characterized by hyperglycemia resulting from defects in insulin secretion, insulin action, or both." (PMID 35327251, 2022). "The early-phase insulin response was supposed to play a critical role in determining postprandial hyperglycemia." (PMID 36079874, 2022). "Increased same-calendar-day discharges, lowered length of stay, improved hyperglycaemia assessment, reduced use of intravenous insulin infusions and a high level of patient satisfaction." (PMID 36992734, 2022). "Gestational diabetes mellitus (GDM), in general, is a metabolic disorder characterized by hyperglycemia brought on by abnormalities in insulin production, insulin action, or both, as well as increasing pregnancy-related issues." (PMID 36532555, 2022). "Of note, postprandial inflammation was prevented by SGLT-2i, which attenuated both hyperglycaemia and insulin release." (PMID 35503137, 2022). "GLP-1 protects against hyperglycemia by inhibiting glucagon secretion from pancreatic α cells, complementing its effect to stimulate insulin, and coordinating the islet hormones leading to lower blood glucose." (PMID 36077491, 2022).